STAT3 (signal transducer and activator of transcription 3)
Diseases named in the same sentence as STAT3 in open-access papers (continued):
Sharing a sentence is not in itself a finding about the gene and the disease.
acute myeloid leukemia (83 papers, 2011 to 2026). Acute myeloid leukemia (AML) is a group of neoplasms arising from precursor cells committed to the myeloid cell-line differentiation. "STAT3 inhibition also causes a reduction in ARG1 expression in patients with acute myeloid leukemia (AML), partially restoring T cell proliferation." (PMID 39337272, 2024). "Furthermore, MDS and acute myeloid leukemia (AML) are strongly associated with sustained, dysregulated activation of STAT3/5." (PMID 40519492, 2025). "The study of childhood forms of acute myeloid leukemia (AML) revealed that the patients whose AML cells exhibited low STAT3 activation had a lower event-free survival compared to the patients with a stronger STAT3 response." (PMID 36765714, 2023). "Studies have shown that STAT3 regulates MYC expression in acute myeloid leukemia (AML), thereby controlling SLC1A5 transcription and OXPHOS and promoting the survival of leukemia stem cells." (PMID 36902385, 2023). "A recent study showed that inhibiting OGA promotes the differentiation of CD34+ hematopoietic stem and progenitor cells (HSPCs) and acute myeloid leukemia (AML) cells into DC via STAT3/5 signaling." (PMID 37675125, 2023). "Recently, Wang lab found that the STAT3 inhibitor SD-36 can effectively degrade STAT3 protein and severely suppress the growth of a subset of acute myeloid leukemia by inducing cell arrest and apoptosis." (PMID 36656267, 2023). "In a different study, the signal transducer and activator of transcription 3 (STAT3) was shown to be a mediator of OXPHOS in LSCs derived from primary human acute myeloid leukemia (AML) specimens." (PMID 36497394, 2022). "The STAT3 isoform STAT3β has been described as a tumor suppressor, which can be a protective prognostic marker in acute myeloid leukemia, especially in ESCC patients with adjuvant chemoradiotherapy." (PMID 33670049, 2021). "C188‐9 was recently identified to target the phosphotyrosine peptide‐binding site within the STAT3 SH2 domain, inhibiting granulocyte colony‐stimulating factor‐induced STAT3 phosphorylation and inducing apoptosis in acute myeloid leukemia cell lines." (PMID 34056872, 2021). "Another neoplasm in which STAT3 has been linked to Birc5 is acute myeloid leukemia (AML)." (PMID 33557010, 2021). "Atovaquone is found to inhibit STAT3 in thyroid cancer, acute myeloid leukemia (AML), and glioblastoma, therefore decreasing cell viability and inducing apoptosis in these cancers." (PMID 33028364, 2020). "C188-9, a new and effective STAT3 inhibitor targeting SH2 domain, was first reported to inhibit granulocyte-colony stimulating factor (G-CSF)-induced Stat3 phosphorylation and induce apoptosis of acute myeloid leukemia (AML) cell lines and primary samples." (PMID 32457835, 2020). "Other studies showed that STAT3 signal transduction pathway induces SOCS-3 in acute myeloid leukemia cells and in rat astrocytes." (PMID 29234375, 2017). "The phosphorylation of STAT3 by integrin β2 was reported recently in acute myeloid leukemia and cutaneous T-lymphoma." (PMID 26848618, 2016). "HNK plays an anticancer role in acute myeloid leukemia by inhibiting STAT3 signaling." (PMID 34539403, 2021). "Recently, it was also found that β2 integrin could activate Syk/STAT3/5 signaling pathway and induce cell division in acute myeloid leukemia cells." (PMID 28345605, 2017). "Finally, the inclusion of STAT1, STAT5B, and STAT3 is of relevance given the cross talk between retinoid receptors and this group of transcription factors in acute myeloid leukemias." (PMID 25888236, 2015).
acute myeloid leukemia (continued). "S727 phosphorylation of STAT3 has also been found to be constitutive in hematological malignancies (e.g., B-cell derived tumors and pediatric acute myeloid leukemia); however the only oncogenes that we are aware of that lead to S727 but not Y705 phosphorylation belong to the Ras family." (PMID 24312439, 2013). "Signal transducer and activator of transcription 3 (STAT3) is frequently overexpressed in patients with acute myeloid leukemia (AML)." (PMID 38806478, 2024). "Besides, it has been shown that STAT3 regulates the transcriptional activity of MYC gene in primitive acute myeloid leukemia cells, invoking the possibility that NCAPG2 might interact with STAT3 and subsequently activate c-MYC expression." (PMID 38166947, 2024). "OPB-111077 is a novel, highly specific oral signal transducer and activator of transcription 3 inhibitor that has exhibited good efficacy against solid and blood cancers, including acute myeloid leukemia (AML), in preclinical models." (PMID 38938528, 2022). "Inhibiting STAT3 reduces autophagy and tumor growth in the context of acute myeloid leukemia (AML) both in vivo and in vitro." (PMID 33573362, 2021). "In cytogenetically normal acute myeloid leukemia, ME1 activates the interleukin (IL)-6/Janus kinase 2 (JAK2)/signal transducer and activator of transcription 3 (STAT3) pathway, which correlates with poor prognosis." (PMID 39996805, 2025). "In addition, exosomal circ_001264, derived from acute myeloid leukemia (AML) cells, activates the p38/STAT3 signaling axis by regulating RAF1 levels, followed by activating macrophage polarization toward the M2 type and elevating PD‐L1 expression." (PMID 39584047, 2024). "In 1996, pioneering works demonstrated that STAT3 and/or STAT5 are constitutively activated in leukemic cells from patients with acute myeloid leukemia (AML) or acute lymphoblastic leukemia (ALL)." (PMID 31963765, 2020). "Furthermore, mutant KIT in acute myeloid leukemia (AML) cells triggers autophagy via STAT3 activation." (PMID 32325894, 2020). "Another STAT3 inhibitor, OPB-111077, has completed a phase I trial for solid cancers (NCT02250170), and phase I/II trials are recruiting for acute myeloid leukemia (AML) (NCT03197714) and other refractory tumors (NCT03158324)." (PMID 31817042, 2019). "Its overexpression has been seen in malignant hematopoietic stem cells (HSCs) in Acute Myeloid Leukemia (AML) and Myelodysplastic syndrome MDS, thus insinuating that STAT3 plays a crucial role in the development of malignancies." (PMID 30217007, 2018). "It has previously been shown that Ang-1 can stimulate phosphorylation of STAT-1, STAT-3, STAT-5 and STAT-6 in human acute myeloid leukemia cells, although the physiological consequences of this were not identified." (PMID 24404127, 2014). "The growth and progression of acute myeloid leukemia cells are supported by a constitutively high expression of STAT proteins, importantly STAT3 & STAT5." (PMID 25383546, 2014). "To extend these results from experimental murine cells to human tumor cells, we examined the STAT3 S727 phosphorylation and its inhibition by PD0325901 in the human acute myelocytic leukemia cell line, THP-1, which express mutant N-Ras." (PMID 24312439, 2013). "In acute myeloid leukemia (AML), OC may enhance responses to FLT3 inhibitors such as gilteritinib by suppressing STAT3-mediated survival signals in FLT3-ITD mutant cells." (PMID 40564985, 2025). "Moreover, the STAT3–MYC axis regulates the neutral amino acid transporter SLC1A5, controlling the influx of glutamine into acute myeloid leukemia cells, maintaining their energy metabolism and survival." (PMID 39534558, 2024).
acute myeloid leukemia (continued). "C188-9 is also a novel and potent STAT3 inhibitor targeting the SH2 structural domain and was first reported to inhibit granulocyte colony-stimulating factor-induced STAT3 phosphorylation and promote apoptosis in acute myeloid leukemia cell lines." (PMID 36291659, 2022). "The first two pathways that are worth mentioning are associated (i) with the ErbB receptor signaling and (ii) with genes (c-KIT, STAT3, AKT3) that have been mainly described as increased in acute myeloid leukemia, in which the crucial role of CEBPA has been widely demonstrated." (PMID 26496024, 2016). "Promoter methylation of PTPN6 occurs in acute myeloid leukemia (AML) cells; indeed, treatment with 5-Azacytidine (5-AZA), an inhibitor of the DNA methyltransferase (DNMT) 1, upregulated PTPN6, thereby resulting in STAT3 inhibition." (PMID 38534772, 2024). "SD-91, the CRBN E3 ligase-based STAT3 PROTAC, led to complete tumor regression in mouse xenografts of MOLM-16 acute myeloid leukemia (AML)." (PMID 39872303, 2023). "It has been published that CGRP has chemotherapy resistance in acute myeloid leukemia (AML) cell lines via the CGRP/CALCRL axis and promotes prostate tumor growth in murine models, possibly via ERKs/STAT3 signaling." (PMID 36582785, 2022). "A previous study suggests that acquired up-regulation of OPN-b and c isoforms might prevent conventional chemotherapy drug (Daunorubicin, Cytarabine and Idarubicin)-induced apoptosis in acute myeloid leukemia (AML) cells by upregulating the expression of AKT, VEGF, STAT3, CXCR4, and IL-6." (PMID 34359989, 2021). "Our recent study showed that acute myeloid leukemia (AML) cells expressing SULT1A1 are highly sensitive to NSC-743380, a small molecule that inhibits STAT3 activity and induces SULT1A1-dependent apoptosis of various cancer cell lines." (PMID 29254232, 2017).
oral cancer (83 papers, 2014 to 2026). "We also demonstrated that COC inhibited STAT3 phosphorylation in oral cancer cells, and these inhibitory effects caused apoptosis and prevented migration." (PMID 40027184, 2025). "GSEA of CAFs activated by oral cancer-derived EVs revealed upregulation of several pathways linked to inflammation including TNFα, IL6_JAK_STAT3 pathway, and IL2_STAT5 signaling pathway." (PMID 37745296, 2023). "STAT3 phosphorylation and subsequent nuclear translocation is implicated in cellular invasion and angiogenesis in oral cancer." (PMID 35884919, 2022). "It has been shown that CCL4 stimulates VEGF-C expression by activating the JAK2/STAT3 signaling pathway, which is frequently linked with oral cancer cell proliferation, invasion, and angiogenesis." (PMID 32961854, 2020). "ME suppressed STAT3 phosphorylation in oral cancer cells, and 53 genes associated with STAT3 signaling were suppressed in the tumors of ME-treated mice." (PMID 32264893, 2020). "The JAK2/STAT3 signaling pathway is implicated in cell invasion and angiogenesis in oral cancer, as well as head and neck metastasis." (PMID 29599774, 2018). "For instance, JAK/STAT3 signaling is associated with oral cancer cell proliferation, invasion and angiogenesis, while STAT3 signaling induces LEC migration and tube formation." (PMID 29599774, 2018). "Our findings revealed that the combination of TW-37 and cryptotanshinone further enhanced the chemosensitivity of human oral cancer cell lines than a single drug alone, which was, perhaps, caused by the inhibition of STAT3–Mcl-1 signaling, thereby validating H2 of this study." (PMID 32863764, 2020). "Given its multifaceted involvement in cellular processes, exploring the role of STAT3 in the regulation of oral cancers becomes particularly intriguing." (PMID 40444012, 2025). "For instance, P. gingivalis promoted cell invasion and proliferation in an oral cancer mouse model via JAK1/STAT3 signaling pathway activation and EMT in tumor microenvironment (TME)." (PMID 40002861, 2025). "More importantly, our study also showed that blockade of EUDAL/EGFR/STAT3/autophagy signaling can sensitize tumor cells to chemotherapy and that the EUDAL/EGFR/STAT3/autophagy signaling status can predict the drug response in patients with oral cancer." (PMID 40940319, 2025). "A high EUDAL/EGFR/STAT3/autophagy pathway activation predicts poor response to chemotherapy in oral cancer patients." (PMID 40940319, 2025). "Mechanistically, it was revealed that STAT3 closely regulated inflammation in oral cancer cells, and the use of stattic significantly compromised the inhibitory effects of IL-37 on the growth of oral cancer cells and the promotive effects on apoptosis." (PMID 40444012, 2025). "Overexpression of STAT3 promotes tumor progression, therapeutic resistance, and angiogenesis of oral cancer cells 30-32." (PMID 40027184, 2025). "In this study, we identified a novel miR-876/SOCS4/STAT3/PD-L1 regulatory axis in oral cancer, which promotes cancer stemness and progression, ultimately leading to recurrence and poor prognosis." (PMID 40140827, 2025). "This study observed that the STAT3 inhibitor stattic robustly compromised TNF-α-induced upregulation of inflammation-related genes in oral cancer cells, emphasizing the significant role of IL-37 in modulating inflammation in these cells." (PMID 40444012, 2025). "Collectively, these findings demonstrate that IL-37 regulates the growth, proliferation, and apoptosis of oral cancer cells via STAT3." (PMID 40444012, 2025). "Our results indicated that Chaga mushroom extract was likely to decrease the level of p-STAT3 in oral cancer cells, thereby suppressing cell growth and glycolysis by inhibiting the STAT3 signaling pathway." (PMID 38720012, 2024). "It has been suggested that IL-6/STAT3 signaling is essential for the survival of CSCs in oral cancer." (PMID 39272862, 2024).
oral cancer (continued). "Concerning other non-cancer studies of SAMA, the potential role of TrxR and other signal transductions, such as NF-κB and STAT3, in suppressing oxidative stress warrants an advanced assessment in oral cancer treatment." (PMID 38399445, 2024). "An intriguing aspect is the suggestion that IL-6 plays a significant role in oral cancer by activating the STAT3 pathway." (PMID 38672565, 2024). "Hesperidin inhibited PD-L1 expression by inactivating the STAT1 and STAT3 signaling molecules in oral cancer cells." (PMID 37446814, 2023). "A recent study has shown that stimulation of oral cancer cells with CCL18 led to the activation of STAT3 signaling pathway that plays an important role in the growth and EMT process in cancer." (PMID 36217054, 2023). "The oral microbiota in periodontitis directly activates IL-17+γδ T cells, stimulates signal transducer and activator of transcription 3 (STAT3) pathway, and promotes infiltration of oral carcinoma tissue with M2-tumor-associated macrophages." (PMID 37373022, 2023). "In summary, thyroxine via integrin αvβ3 activated ERK1/2 and STAT3 to stimulate the PD-L1-dependent and β-catenin-related growth in oral cancer cells." (PMID 36231010, 2022). "Many natural compounds are known to affect STAT3, which is known as one of the major upstream molecules of Mcl-1 in oral cancers." (PMID 35524332, 2022). "In order to determine the mechanisms underlying CCL4-mediated angiogenesis of oral cancer, we treated OSCC cells with CCL4 for 120 min and observed time-dependent increases in STAT3 phosphorylation." (PMID 35884919, 2022). "Recently, IL-6 has been shown to stimulate migration of oral cancer cells via the phosphorylation of STAT3." (PMID 34063134, 2021). "The result was in agreement with Yuan’s finding that EGCG treatment resulted in alteration of AKT/STAT3 signaling and downregulation of Bcl-2 in oral-cancer CAR cells." (PMID 33747527, 2021). "IL-6 and IL-8 promote EMT and cell invasion, which is potentially related to the STAT3 signaling pathway in oral cancer." (PMID 34063134, 2021). "This study demonstrates that TW-37 alone and in combination with cryptotanshinone exerts a potent apoptotic effect on human oral cancer cell lines by inhibiting STAT3–Mcl-1 signaling." (PMID 32863764, 2020). "Blueberries, a rich source of anthocyanins, and malvidin inhibit STAT-3 (signal transducers and activators of transcription-3), which prevents the proliferation and induces the apoptosis of oral cancer cells in vitro, a result further confirmed in vivo." (PMID 32486484, 2020). "ME inhibits mitochondrial respiration at complex I of the electron transport chain, oxidizes peroxiredoxins, activates AMPK, and inhibits STAT3 phosphorylation, resulting in inhibition of the growth and proliferation of oral cancer cells." (PMID 32264893, 2020). "The results showed that these STAT3 inhibitors significantly decreased the cell viability and induced apoptosis in human oral cancer cell lines via the downregulation of Mcl-1." (PMID 32863764, 2020). "We optimized the concentrations of TW-37 and cryptotanshinone to exclude their direct cytotoxic efficiency on human oral cancer cell lines to investigate the synergistic effect of TW-37 with cryptotanshinone as a potent STAT3 inhibitor." (PMID 32863764, 2020). "We demonstrated that ME suppresses mitochondrial respiration and increases ROS generation which leads to Prx oxidation, AMPK activation, and the inhibition of STAT3 in oral cancer cells." (PMID 32264893, 2020). "Consistently, we observed a reduction of the STAT3 phosphorylation at Tyr705 in a concentration-dependent manner in other human oral cancer cell lines, including Ca9.22, HSC-4, and HN22." (PMID 32863764, 2020). "The 14-3-3ζ proteins promote immunity by regulating TLR-3 signaling through TICAM-1 pathway and immune responses through Stat3 signaling in oral cancers." (PMID 29966317, 2018).